CYP21A2 (cytochrome P450 family 21 subfamily A member 2)
Diseases named in the same sentence as CYP21A2 in open-access papers (continued):
Sharing a sentence is not in itself a finding about the gene and the disease.
congenital adrenal hyperplasia (continued). "Congenital adrenal hyperplasia (CAH) is an autosomal recessive disorder, commonly caused by variants in CYP21A2 (chr6p21.33), which encodes the 21-hydroxylase enzyme." (PMID 41571809, 2026). "Congenital adrenal hyperplasia (CAH) is an autosomal recessive disorder with cortisol synthesis impairment, commonly due to CYP21A2 gene mutations." (PMID 40091987, 2025). "Congenital adrenal hyperplasia (CAH) refers to a group of seven monogenic adrenal disorders, caused by pathological variants in genes coding for enzymes in the adrenal steroidogenic pathway: CYP21A2, CYP11B1, CYP17A1, HSD3B2, STAR, CYP11A1, and POR." (PMID 41450580, 2025). "As a result, the patient develops congenital adrenal dysfunction (congenital adrenal hyperplasia, CAH) due to 21-hydroxylase enzyme deficiency, a product of the CYP21A2 gene." (PMID 39512309, 2024). "The data, therefore, suggest that these C11-oxo C21 steroids would be the predominant metabolites, which is of particular relevance in congenital adrenal hyperplasia (CAH) caused by mutations in cytochrome P450 21A2 (CYP21A2), resulting in 21-hydroxylase deficiency (21OHD)." (PMID 38203272, 2023). "This technology was first reported in the context of NIPD for several autosomal recessive conditions, including cystic fibrosis (CFTR), β-thalassaemia (HBB), and congenital adrenal hyperplasia (CYP21A2)." (PMID 39698301, 2023). "Congenital adrenal hyperplasia (CAH) is a group of autosomal recessive disorders of steroidogenesis of the adrenal cortex, most commonly due to 21-hydroxylase deficiency caused by mutations in the CYP21A2 gene." (PMID 36399318, 2023). "Congenital adrenal hyperplasia (CAH), screened for in neonates, is the second most common endocrinopathy after congenital hypothyroidism.Newborn screening for CAH due to CYP21A2 deficiency is performed by immunologic assay for 17-hydroxyprogesterone (17-OHP)." (PMID 36975848, 2023). "In this context, CYP21A2 enzyme is the most frequently affected in patients with congenital adrenal hyperplasia (CAH), leading to an excessive response of 17-hydroxyprogesterone (17OHP) to ACTH1-24." (PMID 35731238, 2022). "Congenital adrenal hyperplasia (CAH) is an autosomal recessive disorder that, in the vast majority of cases, develops due to a mutation of sequence of the CYP21A2 gene." (PMID 36382053, 2022). "Adrenal insufficiency in paediatric patients is mostly due to congenital adrenal hyperplasia (CAH), a severe monogenic disease caused by steroid 21-hydroxylase deficiency (21-OHD, encoded by the CYP21A2 gene) in 95% of cases." (PMID 35422767, 2022). "21-hydroxylase deficiency (21OHD), the most common form of congenital adrenal hyperplasia (CAH), is associated with pathogenic variants in CYP21A2 gene." (PMID 35807105, 2022). "Congenital Adrenal Hyperplasia (CAH), often caused by defects in steroid 21-hydroxylase (CYP21A2), is an autosomal recessive disorder affecting adrenal steroid biosynthesis, leading to impaired glucocorticoid production." (PMID 36047744, 2022). "Our data now provide evidence for the association between POR polymorphisms and clinical features of congenital adrenal hyperplasia, thereby establishing POR as a genetic modifier of CYP21A2 defects." (PMID 33666875, 2021). "We then apply PB-Motif to 26 clinical samples, characterizing CYP21A2 and its pseudogene CYP21A1P as part of a diagnostic assay for congenital adrenal hyperplasia." (PMID 34394200, 2021). "The most common form of congenital adrenal hyperplasia (CAH) results from a deficiency of the 21-hydroxylase enzyme (21-OHD), presenting with a broad spectrum of clinical phenotypes according to the CYP21A2 gene mutations." (PMID 33809035, 2021). "Congenital adrenal hyperplasia (CYP21A2, CYP11B1, HSD3B2, CYP17A1, POR defects) constitutes the largest subgroup of impaired steroidogenesis and represents the most common cause of PAI in children." (PMID 27485500, 2016).
congenital adrenal hyperplasia (continued). "21-Hydroxylase deficiency (21-OHD) is the most common cause of congenital adrenal hyperplasia (CAH), resulting from deletions or mutations of the P450 21-hydroxylase gene (CYP21A2)." (PMID 23484098, 2013). "In a recent study, we have successfully used structural calculation techniques in studies of mutants in human steroid 21-hydroxylase (CYP21A2), causing congenital adrenal hyperplasia." (PMID 19558493, 2009). "Congenital adrenal hyperplasia (CAH) stems from inherited enzyme deficiencies that impair cortisol synthesis, with 21-hydroxylase deficiency accounting for 95% to 99% of cases, caused by mutations in the CYP21A2 gene." (PMID 41424912, 2026). "CYP21A2 is also affected in Congenital Adrenal Hyperplasia, leading to secondary PORD." (PMID 40535332, 2025). "Congenital adrenal hyperplasia (CAH) encompasses a group of autosomal recessive disorders characterized by defects in enzymes critical for steroidogenesis, with 21-hydroxylase deficiency due to mutations in the CYP21A2 gene being the most prevalent form." (PMID 40411327, 2025). "In humans, pseudogene-derived mutations transferred to CYP21A2 by gene conversion or promoter alterations can result in non-classical congenital adrenal hyperplasia (NC-CAH), with measurable effects on transcriptional efficiency." (PMID 41300825, 2025). "A germline mutation in CYP21A2 causing complete absence of CYP21A2 activity leads to congenital adrenal hyperplasia." (PMID 40386408, 2025). "Nonclassic adrenal hyperplasia caused by abnormalities in CYP21A2 affects a percentage ranging from 1 to 10% of women with excessive hair growth, depending on their ethnic background." (PMID 39544240, 2024). "Congenital adrenal hyperplasia includes a group of autosomal recessive disorders, the most common of which is non-classical congenital adrenal hyperplasia (NCAH) caused by mutations in the CYP21A2 gene." (PMID 34071512, 2021). "Congenital adrenal hyperplasia (CAH) (OMIM# 201910) comprises a family of autosomal recessive disorders that are characterized by a group of enzymatic defects in cortisol biosynthesis due to defects in the steroid 21-hydroxylase gene (CYP21A2, OMIM*613815)." (PMID 33552137, 2020). "Nonclassical congenital adrenal hyperplasia due to 21-hydroxylase deficiency is caused by mutations in the active 21-hydroxylase gene (CYP21A2)." (PMID 32647925, 2020). "Congenital adrenal hyperplasia (CAH) due to 21-hydroxylase deficiency is one of the most technically challenging monogenic conditions for molecular diagnosis, owing to the complex genomic architecture of the CYP21A2 locus and the extensive homology between the functional gene and its pseudogene." (PMID 42006261, 2026). "Congenital adrenal hyperplasia (CAH), due to 21-hydroxylase deficiency (21-OHD), is an autosomal recessive condition that is caused by mutations in the gene CYP21A2." (PMID 40529825, 2025). "Finally, the CYP21A2 gene, which was output by XP-EHH as selected in Omanis, is well known for its role in cortisol and aldosterone synthesis in the adrenal glands, and deficiency in this gene is the major factor of congenital adrenal hyperplasia." (PMID 36445690, 2022). "The term CAH-X was coined to describe a subset of patients with congenital adrenal hyperplasia (CAH) who display the hypermobility phenotype of Ehlers–Danlos syndrome (hEDS) due to the monoallelic presence of a CYP21A2 deletion extending into the TNXB gene." (PMID 35807105, 2022).
congenital adrenal hyperplasia (continued). "This article presents the data set regarding the functional characterization of mutations in CYP21A2 gene in CAH patients as described in “Functional characterization and molecular modeling of the mutations in CYP21A2 gene from patients with Congenital Adrenal Hyperplasia." (PMID 29892641, 2018). "21-OHase is encoded by the CYP21A2 gene, which is located in the MHC class III region on chromosome 6, and mutations on this gene are the commonest cause for Congenital Adrenal Hyperplasia (CAH)." (PMID 40093006, 2025). "The single laboratory method validations of duplex qPCR assays with hydrolysis probes on CYP21A1P and CYP21A2 genes, residing a CNV (RCCX CNV) and related to congenital adrenal hyperplasia, were performed using 46 human genomic DNA samples." (PMID 36454796, 2022). "Furthermore, analysis of several classic congenital adrenal hyperplasia (CAH) genes (e.g. CYP21A2) can be difficult using targeted capture and NGS because of the presence of a pseudogene." (PMID 27978845, 2016). "In the majority of cases, classical congenital adrenal hyperplasia (CAH, OMIM: 201910) is caused by the complete lack of functional CYP21A2 (CAH is divided in two main forms; a classical one with severe symptoms and a non-classical one with milder symptoms)." (PMID 25210767, 2014). "Hence, humans with reduced activity of CYP21A2 may suffer from congenital adrenal hyperplasia (CAH), which is characterized by decreased production of cortisol." (PMID 34149610, 2021). "NAHR-mediated deletion between TNXB and TNXA leads to loss of CYP21A2, the causal gene of autosomal recessive 21-hydroxylase deficiency (classical congenital adrenal hyperplasia, CAH), as well as C4B, absence of which may contribute to reduced complement 4 production." (PMID 39629471, 2024). "We aimed to characterize a population of Portuguese females suspected of having non-classic congenital adrenal hyperplasia (NC-CAH) due to clinical and biochemical criteria and who have undergone CYP21A2 molecular analysis." (PMID 35289513, 2022). "Concerted evolution caused by non-allelic gene conversion has been described in great ape CYP21 genes, and the same conversion activity is responsible for a serious genetic disorder of CYP21A2, congenital adrenal hyperplasia (CAH)." (PMID 24312389, 2013).
21-hydroxylase deficiency (69 papers, 2008 to 2026). "In 2018 human CYP21A2 cDNA packaged in AAV-Rh10 was intravenously delivered to female mice with 21-hydroxylase deficiency." (PMID 41450580, 2025). "In 95-99% of cases, CAH is caused by variants in CYP21A2 resulting in 21-hydroxylase deficiency, and this autosomal recessive disorder affects approximately one in 15,000 livebirths." (PMID 41450580, 2025). "TNXB haploinsufficiency has also been documented among a cohort of CAH patients with a 21-hydroxylase deficiency due to the gene’s 3′ overlap with CYP21A2, a condition known as CAH-X syndrome." (PMID 40650310, 2025). "The most common variant of CAH, 21-hydroxylase deficiency (21OHD), is the result of pathogenic variants in the CYP21A2 gene and is one of the most common monogenic disorders." (PMID 38785559, 2024). "The most common form of CAH, 21-hydroxylase deficiency (21OHD), which is caused by pathological variants in the CYP21A2 gene, affects 95% to 99% of all CAH cases." (PMID 37862468, 2024). "The genetic similarity and proximity between pseudogene CYP21A1P and functional gene CYP21A2 facilitate various cross-overs accounting for over 90% of all documented mutations linked to 21-hydroxylase deficiency." (PMID 38791102, 2024). "The predominant form of CAH arises from mutations in CYP21A2, causing 21-hydroxylase deficiency (21-OHD)." (PMID 38791102, 2024). "The complex genetic structure of the RCCX CNV complicates further the genetic diagnosis of 21-hydroxylase deficiency, in particular when a haplotypic structure with the segment harboring two CYP21A2 gene copies and one CYP21A1P pseudogene copy is involved." (PMID 37324257, 2023). "Cases were carriers of most (14.7%) of these variants within the CYP21A2 gene that is associated with autosomal recessive congenital adrenal hyperplasia with 21-hydroxylase deficiency." (PMID 37895316, 2023). "Approximately 90% to 99% of cases of CAH are caused by 21-hydroxylase deficiency (21OHD), which is encoded by the cytochrome P450 family 21 subfamily A member 2 (CYP21A2) gene." (PMID 36675589, 2023). "Several genes code for these enzymes, out of which mutations in the CYP21A2 gene resulting in 21 hydroxylase deficiency, contribute to the most common form of CAH." (PMID 35756349, 2022). "CYP21A2 is responsible for 21 hydroxylase activity, mutations in CYP21A2 can lead to 21 hydroxylase deficiency." (PMID 36330159, 2022). "The vast majority of the cases of CAH (95%) are due to 21-hydroxylase deficiency and associated with pathogenic variants in the 21-hydroxylase (CYP21A2) gene." (PMID 31333583, 2019). "It is due to mutations in the active gene CYP21A2 causing varying degrees of impairment of 21-hydroxylase deficiency (21-OHD) activity." (PMID 30178749, 2019). "CAH due to 21-hydroxylase deficiency (21-OH) is a common autosomal recessive disorder caused by defects in the CYP21A2 gene." (PMID 29386111, 2018). "21-Hydroxylase deficiency (21-OHD) is an autosomal recessive disease resulting from mutations in the CYP21A2 gene." (PMID 30113485, 2018). "More than 95% of all cases of CAH are due to 21-hydroxylase deficiency (21-OHD) resulting from defects in the steroid 21-hydroxylase (CYP21A2) gene." (PMID 28487735, 2017). "Approximately, 90% to 95% of CAH is caused by CYP21A2-related 21-hydroxylase deficiency (21-OHD), which leads to increase in adrenal androgen levels." (PMID 28785026, 2017). "The adrenocortical 21-hydroxylase is one of the key enzymes in glucocorticoid and mineralocorticoid biosynthesis, and mutations in the CYP21A2 gene cause the CAH as a result of 21-hydroxylase deficiency." (PMID 27966633, 2016). "More than 90 % of cases result from 21-hydroxylase deficiency (21-OHD) caused by mutations in CYP21A2." (PMID 26671474, 2015). "In the present work, we describe five novel CYP21A2 mutations in patients from Argentina, diagnosed with 21-hydroxylase deficiency." (PMID 21264314, 2011).
21-hydroxylase deficiency (continued). "Mutations in the CYP21A2 gene have been reported in individuals affected with CAH due to 21-hydroxylase deficiency." (PMID 21264314, 2011). "The most common form is caused by CYP21A2 mutations that result in 21-hydroxylase deficiency." (PMID 39519330, 2024). "Different CYP21A2-gene variations cause varying degrees of 21-hydroxylase deficiency (21OHD)." (PMID 36545328, 2022). "This study identifies the spectrum and frequencies of CYP21A2 variants as well as genotype-phenotype correlations in a group of 48 adult patients with CCAH due to 21-hydroxylase deficiency treated in the Department of Endocrinology at the University Hospital in Krakow, Poland." (PMID 35079965, 2022). "Biallelic LOF variants in the CYP21A2 gene are a major cause of 21-hydroxylase deficiency." (PMID 36171209, 2022). "The most common cause is a mutation in the CYP21A2 gene leading to 21-hydroxylase deficiency (21OHD), which results in impaired production of cortisol and increased production of adrenal androgens, leading to virilization of the external genitalia in 46,XX individuals." (PMID 33815285, 2021). "Mutations in the CYP21A2 gene are responsible of CAH due to 21-hydroxylase deficiency." (PMID 24667412, 2014). "It occurs in a number of different populations and suggests that CYP21A1P may carry P453S as an occasional polymorphism and that this pathogenic variant is transferred to CYP21A2 in the same way as the other pathogenic variants frequently causing 21-hydroxylase deficiency." (PMID 31333583, 2019). "Human CYP21A2 cDNA was packaged in AAV-Rh10 and delivered intravenously to mice with 21-hydroxylase deficiency." (PMID 41450580, 2025). "It is primarily caused by 21-hydroxylase deficiency (21-OHD) resulting from CYP21A2 mutations." (PMID 38791102, 2024). "21-Hydroxylase deficiency (21-OHD; MIM #201910), the most common form of CAH, arises from mutations in the CYP21A2 gene, resulting in virilization of the external genitalia in affected females, early puberty in males, and short stature." (PMID 38699383, 2024). "21-hydroxylase deficiency (21-OHD), the most common form of congenital adrenal hyperplasia, is an autosomal recessive disease caused by mutations in CYP21A2 and has an incidence of 1:15,000-18,000 births." (PMID 36843618, 2023). "ARC 204 was previously diagnosed with in-born 21-hydroxylase deficiency, and MLPA confirmed the presence of the CYP21A2 variant." (PMID 36072675, 2022). "The most common form of congenital adrenal hyperplasia, 21-hydroxylase deficiency (21-OHD), is an autosomal recessive disease caused by mutations in CYP21A2 and has an incidence of 1:15,000-18,000 births." (PMID 35140686, 2021). "Given that the POR gene is located on chromosome 7 and CYP21A2 on chromosome 6, linkage disequilibrium between rs2228104 and CYP21A2 mutations associated with non-classic 21 hydroxylase deficiency appears unlikely." (PMID 33666875, 2021). "None of the other POR polymorphisms or haplotypes were associated with increased risk of either classic or non-classic 21 hydroxylase deficiency or CYP21A2 defect grouping." (PMID 33666875, 2021). "This unusual clinical condition and lack of a mutation in CYP21A2 gene led to doubt concerning the security of the diagnosis of 21-hydroxylase deficiency." (PMID 30074481, 2019). "This important observation, together with the lack of mutation in CYP21A2, encouraged us to reconsider a diagnosis of 21-hydroxylase deficiency." (PMID 30074481, 2019). "Genetic testing for nonclassical 21-hydroxylase deficiency CAH was recommended but declined, although based on the personal and family history, it is assumed that a mutation in the CYP21A2 gene would be most consistent with the phenotype." (PMID 41424912, 2026).